TNF (tumor necrosis factor)
Diseases named in the same sentence as TNF in open-access papers (continued):
Sharing a sentence is not in itself a finding about the gene and the disease.
meningitis (continued). "In addition to such direct effects, intrathecally administered immunoglobulin may neutralize inflammatory cytokines aggravating meningitis, such as interleukin-1 and tumor necrosis factor, as shown by dexamethasone for bacterial meningitis." (PMID 24900929, 2014). "Meanwhile, these factors were also elevatedin the control group compared to the healthygroup, which aligns with previous research and indicatesa clear elevation of that CRP, TNF-α, IL-6, PCT,and IL-1β in children with refractory purulent meningitis." (PMID 39139150, 2024). "Compared to other types of meningitis, several cytokines such as interferon gamma (IFN-γ), tumor necrosis factor alpha (TNF-α), interleukin (IL)-1β, IL-6, and IL-10 are upregulated in the CSF of TBM patients." (PMID 38047697, 2024). "Predictive efficacy of CRP, TNF-α, IL-6, PCT and IL-1β in children with refractory purulent meningitis treated with dexamethasone." (PMID 39139150, 2024). "Through multivariate Logisitic regression analysis, it was determined that CRP, TNF-a, IL-6, PCT, and IL-1 were reliable predictors of the efficacy of Dexamethasone treatment in children with refractory purulent meningitis." (PMID 39139150, 2024). "During meningitis, the permeability of BBB and the expression of cytokines IL-1β, IL-6 and TNF-α increased." (PMID 36555174, 2022). "The expression of TNF-α, IL-6, and IL-1β in the APEC XM group was in line with that previously reported in in vivo or in vitro E. coli meningitis studies." (PMID 34529552, 2021). "More significantly, all vital biotargets of calycosin-anti-meningitis were eventually identified, including EGFR, TNF, EGF, ATM, ESR1, CASP8, NGF." (PMID 33031061, 2020). "The results from this study demonstrate a storm of inflammatory cytokines, such as IL1-α, IL-1β, IL-6, IL-18, TNF-α, and INF-γ, in the 24-h meningitis group." (PMID 31901235, 2020). "In the hippocampus, we observed increased levels of pro-inflammatory cytokines, such as IL1-α, IL1-β, IL-6, IL-18, TNF-α, and INF-γ (P < 0.05) in the 24-h meningitis group." (PMID 31901235, 2020). "As expected, in the PFC, we observed increased levels of pro-inflammatory cytokines such as IL1-α, IL1-β, IL-6, IL-17, TNF-α, and INF-γ (P < 0.05) and decreased levels of IL-7, IL-10, and IL-13 (P < 0.05) in the 24-h meningitis group." (PMID 31901235, 2020). "We have also demonstrated the production of other inflammatory cytokines in the brain during meningitis by TIGR4, as indicated by the TNF-α and IL-1β relative gene expression increase." (PMID 26648922, 2015). "CSF pleocytosis, protein concentration, granulocyte percentage, high tumor necrosis factor-alpha (TNF-α), low glucose and L-arginine during the initial stage of meningitis." (PMID 19814795, 2009). "Because both strains showed excessive TNF, we compared the treatment response in wt, TLR2-/-, CD14-/-, and CD14-/-/TLR2-/-double knockout mice with meningitis to antibiotic treatment and/or anti-inflammatory treatment with TACE inhibitor." (PMID 17428319, 2007). "Therefore, CRP,TNF-α, IL-6, PCT, and IL-1β can be applied as one ofthe crucial indicators to evaluate the curative effect ofrefractory purulent meningitis in children." (PMID 39139150, 2024). "Notably, CRP andIL-1β demonstrated superior predictive performance,suggesting that CRP, TNF-α, IL-6, PCT, and IL-1β canserve as effective indicators for evaluating efficacy ofdexamethasone treatment in children with refractorypurulent meningitis." (PMID 39139150, 2024). "In patients on anti-tumor necrosis factor (TNF) medications, the disease presents as extrapulmonary or disseminated in 25-48% of cases, with central nervous system involvement still being rare, primarily manifesting as meningitis." (PMID 38222988, 2024). "Moreover, serum and CSF HBP levels were higher in children with purulent meningitis than those with viral meningitis compared to other infection biomarkers, including PCT, CRP, and tumor necrosis factor (TNF)-α." (PMID 38297213, 2024).
meningitis (continued). "Newly-weaned hamsters had higher brain viral load, significantly increased cerebrospinal fluid concentration of TNF-α and CXCL10 and inflammatory damages including mild meningitis and parenchymal vascular congestion, despite sparse expression of nucleocapsid antigen in brain cells." (PMID 37122119, 2023). "The serum proinflammatory cytokines in STSS patients, especially interleukin 6 (IL-6), IL-1β, and tumor necrosis factor (TNF), gamma interferon (IFN-ɣ), IL-12, and monocyte chemoattractant protein 1 (MCP-1), are significantly higher than those in meningitis patients." (PMID 32922370, 2020). "In meningitis pathophysiology, BBB disruption is an obligatory outcome, accompanied by acute inflammatory responses, with the release of multiple inflammatory factors such as TNF-α, IL-1β, IL-6, IL-17A, MCP1, and GRO-α." (PMID 31783671, 2019). "Contrary, in CSF of patients with meningitis caused by N. meningitidis, no tendency was observed for a positive correlation between BPI and either TNFα or IL-6 levels." (PMID 30581431, 2018). "Microglia of P4 neonates born to NV and LMWT-infected mothers presented high levels of IL-6, IL-10 and TNF-α and lacked production of IL-12p40; a Th2 pattern similar to the cytokine profile reported in meningitis and encephalitic cases of listeriosis." (PMID 28903312, 2017). "Proinflammatory cytokines (IL-1β, IL-6, TNFα, MCP-1, MIP-1alpha, and RANTES) and adhesion molecules (CD44 and ICAM-1) were significantly reduced in the cerebrospinal fluids of the α7-/- mice with E. coli meningitis." (PMID 21966399, 2011). "For BD-related neurologic disease including manifestation such as meningitis and myelitis and not specifically NBrIHwCVT, Tocilizumab has been described to be an effective alternative to conventional treatment options e.g. anti-TNF agents." (PMID 38877431, 2024). "Subcytolytic concentrations of SLY upregulated the hCMEC release of TNF-α, which led to an increased expression of PLA2G3, destroyed the integrity of the BBB, and may play an important role in the development of S. suis induced meningitis." (PMID 35743951, 2022). "Our data as well as multiple studies in pediatric meningitis demonstrate that TNF-α, IL-6, and IL-8 are present in the CSF of patients with neurologic infection; however, these are likely not good markers for differentiating shunt infection from meningitis." (PMID 30626412, 2019). "In vivo, anti-inflammatory strategies using for example TNFα-antibodies or reducing the amount of TNF-α in the CSF via inhibition of the TNF-α-converting enzyme (TACE) with doxycycline, improved hearing function and reduced cochlear injury in the context of meningitis." (PMID 31244750, 2019). "The concentrations of the cytokines IFN-γ, IL-6 and TNF and the chemokine CCL2 were not significantly different between the WT and GKO meningitis animals, but a significantly lower concentration of IL-1β in the CSF was observed in the GKOs (p = 0.005)." (PMID 31700009, 2019). "Concentrations of MIF, TNFα, and IL-1β were measured with commercial ELISA in serum and cerebrospinal fluid (CSF) from 36 hospitalized TBE patients, 7 patients with non-TBE meningitis, and 6 controls." (PMID 28646884, 2017). "TNFα concentration correlated with total pleocytosis, lymphocyte count, and AQ only in non-TBE meningitis (p < 0.05)." (PMID 28646884, 2017).
demyelinating disease (74 papers, 2005 to 2026). A broad group of disorders that affect the myelin sheaths that cover the neurons. "Anti-TNF-α drugs have been linked to an increased incidence and activity of demyelinating diseases like GBS." (PMID 40283935, 2025). "Although this is rare, TNF inhibitors are associated with the risk of new-onset or exacerbation of demyelinating disorders and psoriasiform skin lesions." (PMID 41357870, 2025). "Here, we confirmed that such AAbs are in human serum and are increased in two groups presenting innate immunity signatures including the two forms of TNF-α and β that have been associated to autoimmune, neuropsychiatric and demyelinating diseases." (PMID 38485715, 2024). "Unidentified rare neurological symptoms and demyelinating disease associated with the use of anti-TNF agents can be detrimental to patient treatment outcomes." (PMID 39078559, 2024). "TNFi agents can worsen underlying demyelinating disease through disturbance of the TNF/TNF receptor system." (PMID 39403668, 2024). "The administration of anti-TNFα in patients with a predisposition to demyelinating disease increases the risk up to 30%." (PMID 37570367, 2023). "CCL3, IFN-γ, and TNF-α are T helper 1 cytokines and they play a pathogenic role in other demyelinating diseases namely MS in which they drive the recruitment and activation of immune cells and elicit toxic or proapoptotic effects on oligodendrocytes." (PMID 37525026, 2023). "Various demyelinating disorders have been reported in association with anti-tumor necrosis factor α (TNF-α) agents." (PMID 32337619, 2020). "A further rare but specific problem associated with the use of anti-TNF-α treatment is demyelinating disease, which usually mimics multiple sclerosis." (PMID 26199624, 2015). "Proinflammatory cytokines, the mediator molecules of inflammation, such as IFN-γ, TNF-α and IL-1β, have been shown to be derived from macrophages/microglia and have been implicated in the pathogenesis of demyelinating diseases." (PMID 18394170, 2008). "TNFα was expressed by infiltrating blood mononuclear cells, and its expression was well correlated with the extent of demyelination in another genetic demyelinating disease, X-linked adrenoleukodystrophy, and in the MS." (PMID 15813970, 2005). "In addition to corticosteroids and 5-aminosalicylates, the expanding therapeutic landscape of IBD includes biologics and small molecules that modulate immune pathways also implicated in demyelinating disease, including TNF, JAK-STAT, and IL-12/23 signaling." (PMID 41317369, 2026). "With more frequent clinical use of anti-TNF drugs, especially with the advent of biosimilars, their association with demyelinating diseases may become more discernible." (PMID 41658656, 2026). "Conversely, anti-TNF-α therapy may lead to serious infection, demyelinating disease, and associated mortality." (PMID 41010776, 2025). "There may also be an association between TNF inhibitors and demyelinating diseases, so they should be avoided in patients with a history of or a first-degree relative with demyelinating disease." (PMID 40109802, 2025). "Rare side effects reported with the use of anti-TNF medications include demyelinating central nervous system (CNS) disorders secondary to use either as a result of the agents themselves or activation of underlying demyelinating disease." (PMID 39078559, 2024). "Some biological drugs, especially anti-TNFα, may increase the risk of developing demyelinating diseases." (PMID 38979406, 2024). "Although anti-TNFα side effects are relatively rare, their administration might cause neurotoxicity, particularly associated with the development of demyelinating disease." (PMID 37570367, 2023). "Although the relationship between treatment with TNF inhibitors and MS has been established, it is currently unclear whether these pharmacological agents trigger the demyelinating disease or rather exacerbate an asymptomatic underlying neurologic inflammation." (PMID 36009588, 2022).
demyelinating disease (continued). "It has been suggested that TNFα antagonists may increase the risk of demyelinating diseases in patients with RA by about 30%, however, these data are not supported by others." (PMID 24938855, 2014). "Despite this dichotomy, current anti-TNF therapies indiscriminately neutralize TNF itself — suppressing both beneficial and detrimental signaling arms — which has led to well-documented adverse effects including increased risk of infection, demyelinating disease, and impaired tissue repair." (PMID 40470209, 2025). "Given these concerns, anti-TNF-α agents are generally avoided in patients with a personal history of demyelinating disease and used with caution in those with suggestive symptoms or a strong family history." (PMID 41317369, 2026). "For instance, it has been reported that the frequency of demyelinating diseases in patients receiving anti-TNF-α therapy ranges from approximately 0.02% to 0.2%." (PMID 40283935, 2025). "Anti-tumor necrosis factor (Anti-TNF) agents have proven beneficial for the treatment of chronic non-infectious uveitis, yet rare neurological complications and demyelinating disease can occur with their use." (PMID 39078559, 2024). "In the case of demyelinating diseases, it is postulated that there is an activation of the polyomavirus by the TNF inhibitor, triggering the disease." (PMID 35314083, 2022). "Failure to clear the virus from infected cells can result in persistent production of IL-6 and TNF-α, which contribute to demyelinating diseases." (PMID 35805128, 2022). "Overall, anti-TNF agents should be considered as contraindicated in patients with established demyelinating disease." (PMID 34802085, 2022). "Inflammatory cytokines such as interleukin (IL)-1β, IL-2, interferon-γ (IFN-γ), and tumor necrosis factor-α (TNF-α) are key mediators of pathological changes in demyelinating disorders and participate in hemodynamic processes." (PMID 34769074, 2021). "More broadly, our study contributes to elucidating the role of TNF signaling in neuroinflammatory and demyelinating disease, which has been controversial mainly in light of the failure of anti-TNF drugs in MS therapy." (PMID 34359956, 2021). "Adverse effects of anti-TNF α have been discussed intensively as the possible etiology of new-onset demyelination diseases in patients with IBD." (PMID 33578895, 2021). "TNF also has important beneficial functions in demyelinating diseases where it mediates the recruitment and differentiation of oligodendrocyte precursor cells (OPC) and remyelination." (PMID 34565380, 2021). "As a result, the pre-existing demyelinating disease was considered a contraindication for TNF alpha-blockers." (PMID 34804701, 2021). "For example, astrocytes, interferon γ (IFNγ), and tumor necrosis factor (TNF) individually are all known to promote inflammation but also mediate neuroprotective functions in demyelinating disease." (PMID 29690885, 2018). "This has renewed interest in regulation of TNF signaling in demyelinating disease, especially given the limited treatment options for progressive MS." (PMID 29690885, 2018). "Nevertheless, according to the current guidelines, avoiding the use of anti-TNF-α therapy is recommended in patients with a history or familial occurrence of MS or other demyelinating diseases." (PMID 28337644, 2017). "Our findings are consistent with studies on animal models for MS showing the amelioration of EAE after treatment with antibody against IL-12/IL-23p40, and with the involvement of TNF in demyelinating disease." (PMID 27916909, 2016). "In a retrospective analysis aiming to determine the frequency of this adverse event, during a four-year period of 550 rheumatoid arthritis patients treated with anti-TNF-α agents, 6 cases of demyelinating disease were identified." (PMID 26199624, 2015). "Moreover, TNF polymorphism may be associated with anti-TNF therapy-induced demyelinating diseases." (PMID 25216562, 2014).
demyelinating disease (continued). "Because anti-TNF therapy can induce and worsen demyelinating diseases, anti-IL-6 therapy is a potential treatment for patients with RA complicated by MS." (PMID 25216562, 2014). "On the other hand, there are several reports of patients with RA who developed demyelinating diseases during anti-TNF therapy and patients with MS who developed inflammatory arthritis during IFN-β therapy." (PMID 25216562, 2014). "Because anti-TNF therapy can exacerbate demyelinating disease, the anti-IL-6 receptor antibody tocilizumab (TCZ) was started at 8 mg/kg every 4 weeks." (PMID 25216562, 2014). "In vivo and in vitro experiments have suggested a correlative relationship between elevated TNFα and the severity of demyelinating disease." (PMID 22271346, 2012). "Notwithstanding these observations, it remains unclear whether TNF-α blockers unmask pre-existing MS, provoke de novo demyelinating disease, or whether these observations are a result of a greater predisposition or developing another IMID." (PMID 41317369, 2026). "Similarly, TNF inhibitors have been reported to exacerbate demyelinating diseases, and the use of TNF inhibitors is contraindicated in patients with a history of MS." (PMID 40806803, 2025). "Interestingly, these cells produce tumor necrosis factor (TNF- α) and other cytokines, which partake in the pathogenesis of the CNS in demyelinating diseases." (PMID 35682964, 2022). "The detrimental relationship between treatment with TNF inhibitors and demyelinating diseases has been extensively analysed, and a large burden of evidence supports the association, even though exposure to anti-TNF-α seems to carry a not so burdensome hazard of MS." (PMID 36009588, 2022). "Moreover, monoclonal antibody therapies targeting TNF and its receptors (TNFRs) have been shown to potentially induce demyelinating disorders in human." (PMID 32811567, 2020). "The relationship between anti-TNF-α and induction of demyelinating diseases remains unclear, but in a number of cases the chronology of clinical events is suggestive." (PMID 32337619, 2020). "Additionally, careful consideration should be done to avoid anti-TNF therapies in patients with a history of demyelinating disease." (PMID 32337619, 2020). "The mechanisms of demyelinating disease induced by anti-TNF therapy are not clear, but inhibition of TNF leads to IFN-γ production, which is associated with MS." (PMID 25216562, 2014). "These two patients represent a population of patients with a preexisting, asymptomatic demyelinating disease, which may become manifest after anti-TNFα therapy." (PMID 24938855, 2014). "Therefore, we believe that TNFα/TNFR1-mediated secondary inflammation is involved in the progression of pathology in varieties of demyelinating diseases." (PMID 15813970, 2005). "Therefore, complications of demyelinating diseases contraindicate anti-TNF therapy." (PMID 25216562, 2014). "However, there is debate about whether treatment with anti-TNFα blockers unmasks preexisting demyelinating disorders such as multiple sclerosis (MS) or induces de novo demyelination of the central nervous system (CNS) and peripheral nervous system." (PMID 24938855, 2014). "In rodents, TNF in the CNS correlates with EAE disease and transgenic TNF expression within the CNS leads to demyelinating disease." (PMID 29690885, 2018). "In the group treated with the first TNF antagonist plus one csDMARD there was one patient with HIV infection and one with demyelinating disease." (PMID 27821150, 2016). "Two patients in this study failed prescreening and did not receive anti-TNFα therapy because brain MRIs at baseline revealed lesions compatible with demyelinating diseases." (PMID 39078559, 2024). "Among the important cytokines, the effects of TNF-α, IL-1β, IL-6, IFN-α/β, and prostaglandin E2, which either alter the type of T cell responses or inhibit immune responses in the development of demyelinating disease, have been investigated." (PMID 33086489, 2020).